CD4 (CD4 molecule)
Diseases named in the same sentence as CD4 in open-access papers (continued):
Sharing a sentence is not in itself a finding about the gene and the disease.
hepatocellular carcinoma (continued). "A recent study concluded that the accumulation of TIM-3+ CD4+ T cells in tumoral regions favors TIM-3-mediated immunosuppressive functions in hepatocellular carcinoma (HCC) patients." (PMID 35164813, 2022). "This previous report showed that in nonalcoholic fatty liver disease, intrahepatic CD4+ T cells in humans and mice are selectively impaired by the accumulation of mitochondria-derived ROS induced by high volumes of fatty acids, which contributes to hepatocellular carcinoma progression." (PMID 36611881, 2022). "In a mouse model for hepatocellular carcinoma, ectopic expression of IL-33 in tumor cells or hydrodynamical injection of IL-33–expressing plasmids into the liver of tumor-bearing mice inhibited tumor development by promoting effector CD4+ and CD8+ T cell activation and IFN-γ production." (PMID 34209038, 2021). "Lower CD4 counts in HIV-HBV co-infected individuals have been associated with higher levels of HBV viral replication (HBV DNA > 200,000 IU/mL) and may increase the risk of developing hepatocellular carcinoma." (PMID 31752729, 2019). "In a prospective study, despite the short duration of follow-up, patients with shorter CD4+ telomeres have outcomes inferior to those with longer telomeres, with more frequent progression to the composite endpoint of death, first episode of hepatic decompensation or hepatocellular carcinoma." (PMID 20462651, 2010). "However, in the control group, the CD4+ T depletion could partially inhibit the tumor formation in the PBS-treated group, indicating that some regulatory CD4+ T might also participate in the anti-hepatoma activity of the liver." (PMID 19272170, 2009). "A recent report highlighted the close association of the YTH domain family with immune cell infiltration, encompassing CD4+ T cells, CD8+ T cells, B cells, dendritic cells, macrophages, and neutrophils in hepatocellular carcinoma." (PMID 40092485, 2025). "Furthermore, azvudine can suppress the growth of hepatocellular carcinoma (HCC) by regulating CD4+ T and CD8+ T cells in vivo." (PMID 39819859, 2025). "In the context of hepatocellular carcinoma (HCC), the TIL subpopulations most commonly studied include Foxp3+, CD8+, and CD4+ T cells, as well as B lymphocytes, NK cells, and macrophages, all of which are associated with prognostic outcomes." (PMID 40308592, 2025). "Further exploration revealed that this enhancer function is known to act on CD4+, CD8+, and HepG (Hepatocellular carcinoma) cells (SEdb2.0 database,)." (PMID 40724930, 2025). "CIBERSORT analysis demonstrated a positive correlation between CHK1 expression in hepatocellular carcinoma (HCC) and CD4+ memory-activated T cells (r = 0.122, p = 0.018), as well as follicular helper T cells (r = 0.233, p < 6.16 × 10−6)." (PMID 40573296, 2025). "Both HBV and HCV modulate the tumor immune microenvironment of hepatocellular carcinoma (HCC) by impairing T‐cell functionality, leading to CD8+ and CD4+ T lymphocyte dysfunction." (PMID 39240588, 2024). "This systematic review investigates the immunosuppressive environment in HBV-associated hepatocellular carcinoma (HCC), characterized by dysfunctional and exhausted HBV-specific T cells alongside an increased infiltration of HBV-specific CD4+ T cells, particularly regulatory T cells (Tregs)." (PMID 38793588, 2024). "In addition, five immune-related genes (IRGs)-FABP6, CD4, PRF1, EREG, and COLEC10-associated with the tumor microenvironment (TME) were significantly predictive of recurrence-free survival (RFS) and overall survival (OS) in patients with hepatocellular carcinoma." (PMID 39199299, 2024). "We profiled proteomes of cancer tissue as well as monocyte/macrophages, CD4+ and CD8+ T cells, and NK cells isolated from tumors, liver, and blood of 48 patients with hepatocellular carcinoma." (PMID 37388918, 2023). "Aberrant p-STAT3 expression has been identified in peripheral CD4+ and CD8+ T cells and related to development of hepatocellular carcinoma (HCC)." (PMID 37741983, 2023).
hepatocellular carcinoma (continued). "In the study of hepatocellular carcinoma, the antigenicity of ASPH can be used to load ASPH on dendritic cells to induce the production of CD4+ T cells, and the antitumor effect can be achieved through this immune response." (PMID 35965520, 2022). "In hepatocellular carcinoma, GGT1 expression has been positively correlated with the level of infiltration of CD4+ T cells, macrophages, and dendritic cells." (PMID 35387129, 2022). "In addition, ZC3H13 may affect the prognosis of patients with hepatocellular carcinoma by increasing four tumor immune cell (CD4+ T cells, macrophages, neutrophils and dendritic cells) infiltration and thus affecting the prognosis of patients with hepatocellular carcinoma." (PMID 35278064, 2022). "Wang and colleagues observed that in the non-alcoholic steatohepatitis-hepatocellular carcinoma model (NASH-HCC model, STAM) the overall number of CD4+ T cells dropped while the number of Tregs sharply increased coincident with more severe tumor burden." (PMID 36618417, 2022). "For example, in patients with hepatitis B virus related hepatocellular carcinoma (HCC), the expression of Tim-3 on CD4+ and CD8+ T cells was increased." (PMID 34631560, 2021). "Concomitantly, immune evasion of hepatocellular carcinoma (HCC) is supported by the lnc-EGFR, whose upregulation in tumor infiltrating CD4+ T cells also leads to their polarization into Treg cells." (PMID 34943820, 2021). "In summary, cellular immune responses, especially CD4+ and CD8+ T cell-mediated immune responses, are essential for the monitoring of malignant tumors and the control of hepatocellular carcinoma development." (PMID 33435880, 2021). "Increased numbers of intrahepatic CD4+ and CD8+ T cells were observed in NAFLD patients with clinical and histological evidence of fibrosis, cirrhosis, and hepatocellular carcinoma." (PMID 34124102, 2021). "In preclinical studies, vaccination is capable of inducing ASPH epitope-specific CD4+ and CD8+ T-cell responses in both animal and human models of hepatocellular carcinoma." (PMID 35004304, 2021). "It has been reported that CD14+HLA-DR–/low M-MDSCs could induce CD4+CD25+Foxp3+Treg cells when co-cultured with autologous T cells in hepatocellular carcinoma (HCC) patients." (PMID 33384962, 2020). "CTLA-4 is another immunosuppressive molecule, and an in vitro experiment suggested that CD4+ CD25+ Tregs isolated from peripheral-blood mononuclear cells could upregulate the expression of CTLA-4 after being co-cultured with stably HBV-transfected human hepatoma cell lines." (PMID 32547550, 2020). "To investigate the role of PD-L1, CD4, CD8, CD276 and SOCS3 in Hepatocellular Carcinoma, we processed GSE102079 and GSE121248 datasets from Gene Expression Omnibus (GEO)." (PMID 32742491, 2020). "By analogy, DPP4 is shed from the surface of CD4+ T cells by kallikrein-related peptidase 5 (KLK5), and in hepatoma cells Serpin B3 induces overexpression of inactive DPP4." (PMID 33143089, 2020). "A number of studies demonstrating FUZHENG Yiliu’s effects on hepatoma cells have been published showing an increase in CD3+, CD4+ and NK cells in peripheral blood with an increase in IL-2 and TNF-α, thus inhibiting hepatocellular cancer proliferation." (PMID 32372963, 2020). "When presented to CD8+ T or CD4+ T lymphocytes, the epitopes activated specific CTLs to secret high levels of TNF-α and IFN-γ and stimulated specific immune response against hepatocellular carcinoma." (PMID 29805966, 2018). "Finding that PCV1 is able to infect CD4+, CD8+, CD14+, CD19+ and CD56+ human cells, and the observation of productive PCV1 infection in a subclone of a human hepatocellular carcinoma cell line suggests potential risks for humans." (PMID 29165219, 2018). "In vivo blockade of reactive oxygen species inverted NAFLD-induced hepatic CD4+ T lymphocyte reduction and delayed NAFLD-induced hepatocellular carcinoma." (PMID 29167646, 2017).
hepatocellular carcinoma (continued). "HBV-related end-stage liver disease, such as decompensated cirrhosis and hepatocellular carcinoma (HCC), represents a growing cause of morbidity and mortality, notably in patients with low CD4+T-cell counts and high HBV DNA levels." (PMID 26764909, 2016). "When PBMCs were co-cultured with human hepatoma cell lines stably transfected with HBV (HepG2.2.15), the CD4+CD25+ Tregs population increased and upregulated Tregs-related genes." (PMID 25654227, 2015). "HIV-1 target cells—CD4+ T-lymphocytes—and HCV target cells—hepatoma cells—were placed in a single chamber (flask), exposed to both HIV-1 and HCV, and viral replication monitored over time by p24 capsid and core ELISAs, respectively." (PMID 26263487, 2015). "To explore the mechanism of GLPS inhibiting tumor growth in the hepatoma-bearing mice, we investigated the impact of GLPS on the balance of Treg (distinguished as CD4 + CD25+) and Teff (distinguished as CD4 + CD25-) in the tumor." (PMID 25889022, 2015). "Another study confirmed that an increase in the number of CD4+CD25-CD69+ Tregs among both the peripheral blood and liver-infiltrating lymphocytes of hepatocellular carcinoma (HCC) patients were correlated with tumor size, vascular invasion and disease stage." (PMID 24984576, 2014). "Functional analysis demonstrates that the HCV TCR-transduced both CD4+ and CD8+ T cells produce interferon-γ, TNF-α, and to a lesser extent, IL-2 when stimulated with the peptide-loaded targets or HCV+ hepatoma cells." (PMID 20686664, 2010). "Consistent with published results using other hepatoma lines, Huh7.5 enhanced the proliferation of previously TCR-activated CD4+ T cells." (PMID 20730048, 2010). "The infected liver environment was modeled by establishing the co-culture of the human hepatoma cell line, Huh7.5, containing the full-length genome of HCV genotype 1a (Huh7.5-FL) with activated CD4+ T cells." (PMID 20730048, 2010). "In this study, we employed primary or subcutaneous mouse hepatocellular carcinoma (HCC) models and flow cytometry to study the impact of conditional knock-in of Ltbr on CD4+ T cell differentiation and response, particularly the Th17/Treg cell ratio, and its influence on HCC progression." (PMID 40436857, 2025). "For all these reasons, elevated levels of circulating CD4+ CD25+ FoxP3+ Tregs are associated with tumor progression and reduced survival rates in patients affected by hepatocellular carcinoma, and the FOXP3+ Treg/CD4+ T-cell ratio also serves as a prognostic indicator for overall survival." (PMID 38791916, 2024). "Similarly, IL7 was found to increase proliferation of circulating CD4 and CD8 T-cells leading to reduced flank tumor growth in a hepatocellular carcinoma model." (PMID 38554147, 2024). "In a mouse multihit model of hepatocellular carcinoma (HCC), we observed activation of the adaptive immune response and induction of two populations of CD4+ T cells expressing choline acetyltransferase (ChAT), including regulatory T cells and dysfunctional PD-1+ T cells." (PMID 37640929, 2023). "CXCR6 may inhibit the occurrence of hepatocellular carcinoma by mediating the clearance of senescent hepatocytes by NKT cells and CD4+ T cells." (PMID 36090326, 2022). "In the peripheral blood of hepatocellular carcinoma patients, the expression of CENPF was upregulated and was found to be positively correlated with the percentage of CD8+ T cells and negatively correlated with the percentage of CD4+ T cells." (PMID 36644760, 2022). "In hepatocellular carcinoma, the expression of some BrD-family coding genes (BRD1/2/3/4/7/8/9) were significantly positively correlated with the immune-infiltrating degree of B cells, CD8+ T cells, CD4+ T cells, macrophages, neutrophils, and DCs." (PMID 36614001, 2022). "Furthermore, culture supernatants of the hepatoma cell line Huh7 appear to promote CD4 + CD25 + Treg cells proliferation and inhibit CD4 + CD25- T cells proliferation." (PMID 35895169, 2022).
hepatocellular carcinoma (continued). "We reasoned that employing the predictive drugs may target the interaction of macrophages and CD4 naïve T cells, which results in reprogramming of the TME and strengthening of immunosurveillance in primary liver carcinoma." (PMID 36221095, 2022). "In order to investigate immune cells densities in hepatocellular carcinoma, immunohistochemistry was performed using antibodies including α-MPO(neutrophils), α-CD-68(macrophages), α-CD-3(T-cells), α-CD-20(B-cells), α-CD-4(CD4+ T-cells) and α-CD-8(CD8+ T-cells)." (PMID 34104178, 2021). "As we have mentioned, being increased in the CD4+ and CD8+ subtypes in peripheral blood of patients with hepatocellular carcinoma, the p-STAT3 expression can lead to aberrant immunological surveillance, thus promoting the development of hepatocellular carcinoma." (PMID 33435880, 2021). "Interestingly, increased p-STAT3 expression in the CD4+ and CD8+ T cells in peripheral blood of patients with hepatocellular carcinoma can lead to aberrant immunological surveillance, thus promoting the development of hepatocellular carcinoma." (PMID 33435880, 2021). "It has also been reported that Tim-3 is strongly expressed on CD4+ and CD8+ T cells obtained from hepatocellular carcinoma lesions, and these data suggest that the functional relationship between Tim-3 and different T cells may affect the prognosis of HCC." (PMID 34869039, 2021). "In vitro evidence suggested that the allogeneic cell lines, HepG2 and BEL7402, when co-cultured with autologous dendritic cells (DCs), the functional APCs in the body, emerged a positive activation of both CD4+ and CD8+ T cells against autologous hepatoma cells." (PMID 34372912, 2021). "Overexpression of METTL3 suppresses the expression of cytokine signaling factor 2 (SOCS2) through an m6A-YTHDF2-dependent mechanism, which in turn regulates the immunosuppression of CD4+CD25+ Foxp3Treg cells involved in TME and ultimately promotes hepatocellular carcinoma cells growth." (PMID 34858499, 2021). "In addition, there are results showing that memory CD4+ T cells can recognize neoantigens and may lead to cancer remission after immunomodulation in the hepatocellular carcinoma (HCC) microenvironment after treatment with sorafenib." (PMID 32983126, 2020). "Therefore, in this study, we observed the proportion of CD4+CD25+CD127LowTregs in patients with primary hepatocellular carcinoma (HCC) before and after treatment and in healthy people, evaluate the clinical performance of CD4+CD25+CD127LowTregs in patients at high risk of HCC." (PMID 32218692, 2020). "Since hepatocytes/hepatoma cells are CD4-negative cells, by flow cytometry we measured the effects of AGS on expression the candidate receptors for HIV entry on hepatocytes, namely, CXCR4, CCR5 and GalCer (galactosyl ceramide)." (PMID 31835520, 2019). "L. barbarum (Gou-Qi) polysaccharides increase CD4+ and CD8+ T cells in H22 hepatoma bearing mice." (PMID 26828466, 2016). "We present a patient with hepatic cirrhosis and hepatocellular carcinoma who was still found to have PML in the setting of a CD4+ count >200 and a negative viral load." (PMID 27529042, 2016). "CW-HIFU thermal ablation of osteosarcoma, hepatocellular carcinoma, and renal cell carcinoma was found to be accompanied by a marked increase in CD4+ cells at the ablated tumor-tissue margins, but no significant changes in CD8+ or CD3+ cell populations." (PMID 23140567, 2012). "Human 5F7 does not show any significant DNaseI hypesensitivity in the seven cell lines tested (CD4+ T cells, GM06990 lymphoblastoid, HeLa S3 cervical carcinoma, HepG2 liver carcinoma, H9 human embryonic stem, IMR90 human fibroblast, K562 myeloid leukemia-derived)." (PMID 21206754, 2010).
hepatocellular carcinoma (continued). "Our results indicate that both the HCV TCR-transduced CD4+ and CD8+ T cells recognized the HCV NS3:1073–1081 peptide-loaded targets and HCV+ hepatocellular carcinoma cells (HCC) in a polyfunctional manner with cytokine (IFN-γ, IL-2, and TNF-α) production as well as cytotoxicity." (PMID 20686664, 2010). "Here in hepatocellular carcinoma, we used in vivo experiments to demonstrate that cancer cells express Esm1 to inhibit CD4+T cells mediated cancer cytotoxicity, which supports the anti-inflammatory role of ESM1 in HCC development." (PMID 38956432, 2024). "Key markers, such as PTPRC, CD3E, CD4, CD79A, and CD3G in immune cells, EPCAM and KRT19 in epithelial cells, and MME and PECAM1 in stromal cells, were identified, providing crucial insights into hepatocellular carcinoma progression and immune response mechanisms." (PMID 39388011, 2024). "In the dynamic milieu of hepatocellular carcinoma (HCC), the tumor microenvironment (TME) orchestrates intricate interactions with the adaptive immune system, prominently involving CD8+ cytotoxic T cells and CD4+ helper T cells among tumor-infiltrating lymphocytes (TILs)." (PMID 38791916, 2024). "The reduced populations of effector CD4+ T cells and NK cells might impair the process of elimination of activated HSC cells or retained hepatocytes, potentially leading to progression of hepatic fibrosis to cirrhosis or hepatocellular carcinoma." (PMID 35222390, 2022). "In preclinical models of hepatoma and fibrosarcoma, the absence of stromal miR-21 accelerated tumour growth compared to growth in wild type mice and was accompanied by reduced activation of CD4+ and CD8+ T cells." (PMID 35821197, 2022). "In this regard, a study analyzing cancer progression of allograft hepatoma tumors in miR-21-null mice showed that CD4+ and CD8+ T cell responses were weaker in these mice, allowing for a better progression of the allografts, whereas introducing WT CD4+ and CD8+ T cells reversed the phenotype." (PMID 34638467, 2021). "However, it contradicts the study on hepatocellular carcinoma which showed a strong association between VISTA and CD8+TILs rather than CD4+TILs." (PMID 33505908, 2020). "However, if monocytes/macrophages or CD4+T-cells, but not others, were removed, these mice developed hepatocellular carcinoma (HCC)." (PMID 31709183, 2019). "HBsAg-positive cART-treated patients demonstrate impaired CD4 recovery and accelerated evolution towards AIDS3 in addition to increased HBV replication, liver disease progression, hepatocellular carcinoma (HCC) prevalence and liver-related mortality." (PMID 31420570, 2019). "However, through our systematic review and meta-analysis, we got a more unified conclusion that CD3+, CD4+, CD8+, and Foxp3+ could serve as prognostic biomarkers in hepatocellular carcinoma." (PMID 28790445, 2017). "Meanwhile, it increased NK cells’ cytotoxicity in spleen, down-regulated the amount of CD4+CD25+Foxp3+ Treg cells and Th17 cells in tumor tissue, and decreased IL-10, TGF-β, and IL-17A levels (P < 0.01) whereas increased IL-2 and IFN-γ levels (P < 0.01) in the serum of hepatoma H22-bearing mice." (PMID 28086772, 2017). "Similarly, TIM-1+ B cells from patients with HBV-induced hepatocellular carcinoma do not suppress granzyme and perforin production by CD4+ T cells." (PMID 28103916, 2017). "Notably, multi-color immunofluorescence and confocal microscopy demonstrated that Tim-3+Foxp3+CD4+ cells were preferentially distributed in the tumor nest rather than the peritumoral stroma of hepatocellular carcinoma." (PMID 23526963, 2013). "In addition, the CEP55 expression was significantly related to the infiltration level of B cells, CD4+ T cells, CD8+ T cells, macrophages, neutrophils, and dendritic cells in hepatocellular carcinoma (HCC)." (PMID 32337246, 2020).